MTOR (mechanistic target of rapamycin kinase)
Diseases named in the same sentence as MTOR in open-access papers (continued):
Sharing a sentence is not in itself a finding about the gene and the disease.
glioma (continued). "Recent studies have proposed that YME1L is important for Akt-mTOR cascade activation in glioma and NSCLC cells." (PMID 38769124, 2024). "The cardiotonic steroids ouabain have been shown to decrease cell growth and migration of glioma U-87MG by inhibiting the signaling pathway Akt/mTOR." (PMID 39329752, 2024). "KIF3C has also been identified as a factor that can impede glioma growth by modulating the PI3K/AKT/mTOR pathway, thereby extending the survival of glioma patients, and offering a prospective target for glioma treatment." (PMID 38552217, 2024). "Kindlin-2 and GOLPH3 (Golgi phosphoprotein 3) proteins are associated with glioma, and it appears that YBX1 protein is involved in the increased expression of EGFR and the activation of mTOR in this context." (PMID 38255791, 2024). "This gene is involved in the PI3K/Akt/mTOR signaling pathway, which has been confirmed to play an important role in the genesis and development of glioma." (PMID 39767683, 2024). "Zhanget al. revealed that the overexpression of mitochondrial Clk1 impaired chemoresistance through the AMPK/mTOR/HIF-1α-mediated glycolytic pathway in glioma cells." (PMID 38634120, 2024). "Amenflavone (AF) was found to promote ferroptosis with the signaling pathway AMPK/mTOR in glioma cells and endometrial cancer cells." (PMID 38583115, 2024). "miRNAs − 129-mediated suppression Notch1 promotes autophagic flux by suppressing mTOR activity and increasing Beclin-1 expression in glioma cells." (PMID 38965615, 2024). "It has been shown that miRNAs-199a inhibits the growth of liver cancer, glioma, and endometrial cancer by suppressing mTOR expression." (PMID 38965615, 2024). "Examining the potential molecular mechanism, we found that CBX2 inhibits PTEN transcription by recruiting EZH2 to regulate the H3K27me3 level of the PTEN promoter and thus activates the AKT/mTOR pathway to accelerate glioma progression and TMZ chemoresistance." (PMID 39114365, 2024). "Previous studies have shown that the AKT/mTOR signalling pathway is involved in the occurrence, development and chemoresistance of gliomas." (PMID 39114365, 2024). "We show that the combined treatment substantially reduces viability of patient-derived glioma cells, in concordance with the inhibition of prominent oncogenic pathways, including the mTOR pathway." (PMID 39093942, 2024). "Although molecular alterations in the PI3K/Akt/mTOR pathway have been increasingly recognized in canine gliomas, reflecting similarities to the human counterpart, studies addressing abnormalities in PTEN expression are scarce." (PMID 39061577, 2024). "We have previously shown that mTOR inhibition renders LNT-229 glioma cells more resistant towards CCNU as well as vincristin chemotherapy." (PMID 38182566, 2024). "In summary, our results indicate that co-administration of temozolomide chemotherapy and mTOR inhibitors reduces temozolomide efficacy via recovery of ROS homeostasis in MGMT promotor methylated glioma cells." (PMID 38182566, 2024). "The majority of gliomas exhibited activation of the PI3K/AKT/mTOR pathway and RAS–MAPK signaling pathways." (PMID 38714727, 2024). "Activation of PI-3 kinase signaling pathways in gliomas leads to the activation of downstream effector molecules such as Akt and mTOR (the mammalian target of rapamycin), which promote proliferation and resistance to apoptosis." (PMID 38254732, 2024). "Mismatch-positive gliomas also showed upregulated mTOR pathway expression, higher ADC, and lower rCBV compared to their mismatch-negative counterparts." (PMID 37924213, 2024). "CPZ is known to inhibit PI3K/Akt/mTOR in glioma and oral cancer cells, and also induce ER stress in glioblastoma cell lines." (PMID 38177535, 2024). "Another PI3K inhibitor is the combined PI3K/mTOR inhibitor, voxtalisib, which underwent a phase I trial in the treatment of high-grade gliomas." (PMID 38474373, 2024).
glioma (continued). "When GOLPH3 was down-regulated, it resulted in a substantial reduction in the levels of YBX1 and mTOR activity, which are both crucial for glioma cell migration and invasion." (PMID 38255791, 2024). "Meanwhile, enrichment analysis of HIC2 expression suggested that the mTOR signaling pathway was potential HIC2‐mediated pathways in glioma cells." (PMID 36650953, 2023). "All those sparse observations are in favor of the early involvement of the AKT/mTor pathway in BRAF-mutant glioma development." (PMID 36831610, 2023). "miRNA-383-5p and VEGFA/Akt/mTOR pathway play important regulatory roles in the malignant biological behavior of glioma." (PMID 37592783, 2023). "Thereof, anti-cancer drugs targeting P13K/AKT/mTOR would inhibit glioma proliferation, angiogenesis and promote apoptosis." (PMID 37025487, 2023). "Depletion of FilGAP also reduced spheroid diameter in both KINGS-1 and U-87MG, suggesting that FilGAP promotes spheroid growth in glioma as well as mTOR." (PMID 38065968, 2023). "Epigenetic activation of the PI3K/AKT/mTOR pathway is commonly observed in glioma, resulting in selection advantages such as increased metabolism, proliferation, stemness, and invasiveness." (PMID 36647827, 2023). "MAPK4 silencing inhibited proliferation and migration and induced G1 cell cycle arrest in glioma cells via the AKT/mTOR pathway." (PMID 36999945, 2023). "In another study, metformin repressed glioma proliferation through mTOR inhibition by increasing PRAS40, which is an AKT substrate that can bind to RAPTOR to negatively regulate mTOR." (PMID 37278858, 2023). "For instance, in glioma, this lncRNA expressed oncogenic behavior through the mTOR signaling pathway." (PMID 37835380, 2023). "Within this framework, in the present study, we carried out an extensive series of experiments comparing SAP with the selective mTOR inhibitor rapamycin in two different glioma cell lines as well as in models of GBM–microglia interaction." (PMID 37372982, 2023). "Conversely, MST1 overexpression inhibited glioma cell proliferation by modulating the AKT/mTOR pathway." (PMID 37251938, 2023). "have demonstrated that ouabain suppresses the Akt/mTOR signaling pathway and inhibits the growth and motility of U-87MG human glioma cells." (PMID 36856826, 2023). "Compared with m7Gcluster-B, m7Gcluster-A presented a significant survival advantage with inositol phosphate metabolism, phosphatidylinositol, glioma, neurotrophin, ErbB, mTOR, insulin, Wnt signaling pathways as well as other enrichment pathways." (PMID 36998056, 2023). "In glioma, the Wnt/β-catenin signal promotes neurogenesis and cell proliferation while the PI3K/AKT/mTOR pathway is associated with growth, metabolism, autophagy, survival, and chemotherapy resistance of glioblastoma." (PMID 37796789, 2023). "Among the identified components, beta-asarone has garnered attention due to its ability to induce autophagy and inhibit cell proliferation in human glioma U251 cells by strongly inhibiting the mTOR pathway." (PMID 37089953, 2023). "Adding to the list of drugs targeting the AKT/mTOR pathway, metformin has been shown to be an anti-glioma agent." (PMID 37998723, 2023). "In this context, employing drug repurposing approach, we had attempted to trigger apoptosis in glioma via ROS-mediated inactivation of PI3K/AKT/mTOR pathway." (PMID 37025487, 2023). "The PI3K-Akt-mTOR pathway, which modulates cell growth, proliferation, survival, and metabolism, is one of the most important signaling pathways in glioma pathogenesis." (PMID 38275370, 2023). "Among the many molecular interactions that PrP physiologically performs, it appears that processes shared with autophagy activity are those most implicated in glial tumor carcinogeneses such as activity on MAP kinases, PI3K, and mTOR." (PMID 36674920, 2023). "MET decreases mTOR expression alongside increased AMPK expression (an mTOR inhibitor) in human glioma cells." (PMID 37444478, 2023).
glioma (continued). "These proteins upregulate the molecular signaling pathways of gliomas such as the mTOR pathway as well as glutamatergic signaling pathways." (PMID 38275375, 2023). "In this work, we have reported miRNA-383-5p to act as a glioma suppressor and found it to inhibit aggressive glioma cell biological behavior via downstream regulation of VEGFA/mTOR." (PMID 37592783, 2023). "These NSG have been shown to promote glioma cell progression and survival through the activation of several pathways, such as the Akt/mTOR pathway and the MAPK pathway, which are mediated by N-methyl-D-aspartate (a.k.a." (PMID 37500667, 2023). "MAPK4 was found to promote the proliferation and migration of glioma cells via the AKT/mTOR pathway by bioinformatic analyses and experimental verification." (PMID 36999945, 2023). "Dysregulated mTOR signaling sustains the self-renewal capabilities of glioma stem cells (GSCs), a subpopulation of cells with tumor-initiating properties." (PMID 37834408, 2023). "One such pathway is PI3K/AKT/mTOR pathway, a key regulator for glioma survival and proliferation, which has demonstrated to enhance oxidative stress, thereby promoting tumor cell survival in several tumors." (PMID 37025487, 2023). "Several groups have demonstrated that oncogenic transformation and dedifferentiation of glioma precursor cells is reliant on activation of mTOR." (PMID 37395282, 2023). "Literature data also show also mTOR-independent regulation of 4E-BP1 occurs in glioma cells, myoblasts, and acute myeloid leukemia." (PMID 37047048, 2023). "The intra-glioma lactic acid concentration was 12 ​μmol/g in the drug group and was 8.4 ​μmol/g in the nanoparticle group demonstrating the decreased activity of the mTOR pathway." (PMID 37273792, 2023). "In particular, in glioma, one of the malignant brain tumors, activation of the mTOR pathway promotes cell proliferation and invasion, and contributes to patient poor prognosis." (PMID 38065968, 2023). "Nevertheless, the activation of PI3K/AKT/mTOR pathway in glioma leads to the development of drug resistance, thereby inhibiting the therapeutic effect of “T”." (PMID 37025487, 2023). "mTOR signaling is activated in a variety of tumors, including glioma that is one of the malignant brain tumors." (PMID 38065968, 2023). "JW-7–52-1 is a PI3K/MTOR signaling pathway inhibitor that hasn’t been tested for effects in gliomas." (PMID 36845382, 2023). "Previous studies have shown that miR-128 can be used as a tumor suppressor to regulate mTOR signaling to promote apoptosis, reduce the proliferation of tumor cells and inhibit the angiogenesis and growth of gliomas by targeting mRNAs." (PMID 36982952, 2023). "Sato, Sunayama, and colleagues have shown that concurrent inhibition of this pathway and PI3K/Akt/mTOR induces differentiation of undifferentiated glioma stem-like cells via activating FoxO3a transcriptional activity." (PMID 37821870, 2023). "Signaling molecules released by neurons, such as the synaptic protein neuroligin-3 (NLGN3), can influence glioma progression by activation of the PI3K/mTOR pathway." (PMID 36647827, 2023). "The upregulation of miR-16 inhibits the growth of hepatocellular cancer cells and glioma cells through the PI3K/AKT/mTOR signaling pathway." (PMID 37509289, 2023). "Hypoxia or glutamine starvation in glioma cells promotes the phosphorylation of Ser301 Beclin1 by PGK1 through the mTOR inhibition which promotes the activation of autophagic initiation complex, which contributes to the brain tumoral aggressiveness." (PMID 38139462, 2023). "The mTOR (mammalian target of rapamycin) signaling pathway is activated in multiple human neoplasms, which is involved in the crosstalk between microglia and glioma." (PMID 37700840, 2023). "The glutamine antagonis JHU-083 reduced glioma cell growth and disrupted mTOR signaling in glioma cells." (PMID 38139462, 2023).
glioma (continued). "The reduced phosphorylation levels of Akt and mTOR in IRAK1 depletion glioma cells were restored by PRDX1 overexpression, ATG5 knockdown or 3-MA treatment." (PMID 37031183, 2023). "NLGN3 can activate multiple RTKs and the downstream cascades (i.e. PI3K-Akt-mTOR), promoting cell survival and growth in glioma cells." (PMID 37880221, 2023). "Our results indicate that miRNA-383-5p functions as an anti-oncogene by inhibiting the VEGFA/Akt/mTOR signaling pathway in glioma cells." (PMID 37592783, 2023). "GDH activity is reversible, forming either glutamate or αKG and ammonia, but the αKG production is favored in gliomas, this reaction is activated by mTOR and ADP, deficit energy." (PMID 38139462, 2023). "In this sense, omega-3-polyunsaturated fatty acids (ω3-PUFAs), such as docosahexaenoic acid (DHA), have been reported to increase autophagy-like cell death mechanism by activating AMPK and dephosphorylating AKT and mTOR in glioma cells." (PMID 38139462, 2023). "We investigated mTOR because it is an important negative regulator of autophagy and has been experimentally validated as a direct target of miR‐128 in glioma cells." (PMID 36880288, 2023). "Further study showed that hirudin caused a decrease in the phosphorylation of mTOR and its downstream factors ULK1, P70S6K and 4EBP1 and preliminarily showed an inhibitory effect of hirudin on glioma via cell‐derived xenografts (CDXs) in nude mice in vivo." (PMID 37539490, 2023). "Akt inhibits the target of mammalian target of rapamycin (mTOR) in gliomas, which regulates a variety of cellular responses, such as cytoskeletal structure, transcription, and autophagy, to enhance cell viability." (PMID 37783914, 2023). "Gαi1 and Gαi3 are upregulated in human glioma tissues and cells, mediating Akt-mTOR activation to promote glioma cell growth in vitro and in vivo." (PMID 36805440, 2023). "Among these, the PI3K/AKT/mTOR pathway has been reported to be aberrantly activated in almost 80% glioma cases." (PMID 37025487, 2023). "For example, the inhibition of the MEK/ERK pathway leads to activation of PI3K/mTOR signaling, but the combined targeting proved to reduce self-renewal and tumorigenic capacity of glioma stem cells." (PMID 38203299, 2023). "Aberrant activation of PI3K/AKT/mTOR pathway is observed in 80% of glioma cases, thereby emphasizing its significance as a therapeutic target." (PMID 37025487, 2023). "Other in vitro studies however showed that mTOR inhibition under hypoxic conditions can promote survival of glioma cell lines in vitro by reducing oxygen and glucose consumption, and promotes temozolomide resistance by increasing MGMT protein levels." (PMID 37114125, 2023). "In glioma, decorin mostly acts as a suppressor of cancer metastasis by modulating signal transduction in pathways such as c-Met/Akt/mTOR to disrupt EMT." (PMID 37013486, 2023). "Even though ARL4D was previously identified as a glioma-associated antigen dependent on loss of PTEN and consequent activation of Akt/mTOR pathway, its oncogenic roles and underlying molecular mechanisms have never been reported in any cancer type before." (PMID 36273157, 2022). "In the present study, we have confirmed that silvestrol can inhibit glioma through the AKT/mTOR and ERK1/2 signaling pathway." (PMID 35677890, 2022). "Like macrophages, PI3K/AKT/mTOR is the primary signaling pathway that controls the metabolism in glioma cells." (PMID 35392088, 2022). "Dimethylaminomicheliolide is a novel chemotherapeutic agent that induces apoptosis and autophagy by adjusting the ROS/MAPK signaling pathway and inhibiting the Akt/mTOR signaling pathway to treat gliomas." (PMID 35935861, 2022). "A study of the therapeutic effect of Schisandrin B on glioma found that the HOTAIR–miR‐125a–mammalian target of rapamycin (mTOR) pathway plays a key role in proliferation and invasion outcomes." (PMID 35592755, 2022).
glioma (continued). "As autophagy has been shown to promote tumorigenesis in a variety of tumor entities, including gliomas, co-inhibition of mTOR and autophagy seems a plausible treatment approach." (PMID 36202792, 2022). "In terms of mechanism, this study found that CAMK1D regulates the function of glioma cells by the PI3K/AKT/mTOR pathway." (PMID 35494053, 2022). "Mechanistically, BYSL activated the AKT pathway by regulating RIOK2 and mTOR, acting as an oncogene in gliomas." (PMID 35473611, 2022). "The inhibitory effect of curzerene on cell proliferation was reversed upon treatment with an mTOR agonist, indicating that curzerene's ability to inhibit glioma proliferation depends on the downregulation of the mTOR/p70S6K axis." (PMID 35048517, 2022). "For this project, we expanded on the pro-survival effects of mTOR inhibition in glioma cells previously reported by our group." (PMID 36202792, 2022). "Gαi1 can form a complex with multiple RTKs (including FGFR, PDGFR and EGFR), transducing downstream Akt-mTOR activation in glioma tissues and cells." (PMID 35280670, 2022). "The PI3K/Akt/mTOR pathway is overactive in glioma tumors, resulting in enhanced tumor proliferation and reduced apoptosis, and is frequently implicated in resistance to anticancer therapies." (PMID 35328780, 2022). "Taken together, our study shows that inhibition of mTOR protects glioma cells from hypoxia-induced cell death in an autophagy-independent manner." (PMID 36202792, 2022). "As discussed, our group showed that the combination of PDGFRA inhibitor dasatinib with mTOR inhibitor everolimus significantly improved the survival of pediatric high-grade glioma than either treatment alone." (PMID 35978801, 2022). "With respect to the PI3K/AKT/mTOR pathway, the dual PI3K/mTOR inhibitor dactolisib attenuated tumor progression in animal models of glioma, and the allosteric AKT inhibitor MK-2206 presented antitumoral effects in vitro." (PMID 36013437, 2022). "For example, lncRNA LINC00998 can suppress the malignant glioma phenotype via the chromobox 3 (CBX3)-mediated c-Met/Akt/mTOR axis." (PMID 35156508, 2022). "High expression of CXCR4 in glioma was modulated through Akt/mTOR signaling by Notch1, which promotes the migration of glioma-originating cells." (PMID 35571062, 2022). "In particular, a third-generation mTOR inhibitor, RapaLink-1, which inhibits mTORC1 and proliferation in human glioma cells, requires FKBP1A in order to be practical and durable." (PMID 36499275, 2022). "We applied the GSC model to obtain a deeper understanding of the role of the YB-1/CCT4/mLST8/mTOR axis in glioma growth." (PMID 35239512, 2022). "The current study found that RES can activate caspase-3 in glioma cells by blocking the intracellular signaling pathway PI3K/Akt/mTOR." (PMID 35889532, 2022). "Curzerene can induce apoptosis by inhibiting the expression of GSTA4 in gliomas, and it can downregulate the proliferation, invasion, and migration of gliomas by inhibiting the phosphorylation and activation of mTOR and the expression of MMP9." (PMID 35048517, 2022). "The PI3K/Akt/mTOR pathway is hyperactive in glioma tumors, resulting in decreased apoptosis and quicker tumor progression, and it is frequently associated with drug resistance." (PMID 35889532, 2022). "In gliomas, lncRNA CASC2 was displayed as an inhibitor of cell growth through negatively modulating miR-21, whereas lncRNA CRNDE induced cell growth and invasion of glioma via modulating mTOR signaling." (PMID 35341001, 2022). "Circ-0014359 and circ-NT5E promote glioma progression via the PI3K/AKT/mTOR signaling pathway via miR-153 and miR-422a, respectively." (PMID 36358938, 2022). "Recent demonstrated that lncRNA KB-1460A1.5 inhibits glioma tumorigenesis via miR-130a-3p/TSC1/mTOR/YY1 feedback loop." (PMID 35935338, 2022). "Studies revealed that NEAT1 promotes glioma progression via activating several important signaling pathways, including mTOR and Wnt signaling." (PMID 35123484, 2022).